C15orf61 (chromosome 15 open reading frame 61)
Synonyms: LOC145853
Tractability: Antibody: UniProt places it where antibodies can reach, with high confidence; UniProt predicts a signal peptide or a membrane-spanning region; its Gene Ontology location is reachable by antibodies, with medium confidence.
Gene: Protein-coding gene on chromosome 15 (67,521,131 to 67,530,146, forward strand). Ensembl gene ENSG00000189227.
Subcellular location: Secreted
Subcellular location (Human Protein Atlas): Nucleoli; Vesicles; Cytosol; Predicted to be secreted
Gene Ontology:
Cellular component: mitochondrion; extracellular region
Genetic constraint (gnomAD): Loss-of-function variants: 9 observed, 8.41 expected, observed/expected ratio (o/e) 1.07, 90% interval 0.64 to 1.76. That is too few expected variants to judge how well the gene tolerates losing a copy. Missense variants: 200 observed, 138.09 expected, observed/expected ratio (o/e) 1.45, 90% interval 1.29 to 1.63. Synonymous variants: 77 observed, 64.61 expected, observed/expected ratio (o/e) 1.19, 90% interval 0.99 to 1.44.
Homologues: Orthologues: chimpanzee C15H15orf61 (100% identical), macaque C7H15orf61 (98% identical), pig C15orf61 (94% identical), dog C15orf61 (94% identical), mouse 2300009A05Rik (92% identical), guinea pig C15orf61 (88% identical), rat C8h15orf61 (71% identical), tropical clawed frog c3h15orf61 (69% identical), zebrafish C18H15orf61 (62% identical), Drosophila melanogaster CG34148 (43% identical).